RN7SKP146 (RN7SK pseudogene 146)
Gene: Miscellaneous RNA gene on chromosome 18 (586,517 to 586,850, reverse strand). Ensembl gene ENSG00000222174.
Homologues: Orthologues: chimpanzee 7SK (98% identical). Paralogues in human: RN7SKP79 (72% identical), 7SK (71% identical), RN7SKP184 (71% identical), RN7SKP9 (71% identical), RN7SKP180 (70% identical), RN7SKP230 (70% identical), RN7SKP255 (70% identical), RN7SKP71 (70% identical), RN7SKP120 (70% identical), RN7SKP176 (70% identical), RN7SKP203 (70% identical), RN7SKP189 (69% identical), and 284 more.